CC2D1B (coiled-coil and C2 domain containing 1B)
Description:
Transcription factor that binds specifically to the DRE (dual repressor element) and represses HTR1A gene transcription in neuronal cells.
Synonyms: Freud-2; KIAA1836; LGD1
Tractability: PROTAC: ubiquitination databases record sites on it; its protein half-life has been measured.
Gene: Protein-coding gene on chromosome 1 (52,345,723 to 52,366,318, reverse strand). Ensembl gene ENSG00000154222.
Subcellular location: Nucleus
Subcellular location (Human Protein Atlas): Nucleoplasm; Vesicles
Pathways (Reactome):
Cell Cycle: Sealing of the nuclear envelope (NE) by ESCRT-III
Gene Ontology:
Molecular function: protein binding; DNA-binding transcription factor activity, RNA polymerase II-specific; RNA polymerase II cis-regulatory region sequence-specific DNA binding; DNA-binding transcription repressor activity, RNA polymerase II-specific
Biological process: regulation of transcription by RNA polymerase II; negative regulation of transcription by RNA polymerase II
Cellular component: nucleoplasm; nuclear envelope; nucleus; cytosol; endosome membrane
Genetic constraint (gnomAD): Loss-of-function variants: 89 observed, 108.54 expected, observed/expected ratio (o/e) 0.82, 90% interval 0.69 to 0.98. The upper end of that interval is the gene's LOEUF score, 0.98, which puts it in group 4 of 6, group 1 being the genes least tolerant of losing a copy. Missense variants: 1,134 observed, 1,102.8 expected, observed/expected ratio (o/e) 1.03, 90% interval 0.98 to 1.08. Synonymous variants: 406 observed, 431.3 expected, observed/expected ratio (o/e) 0.94, 90% interval 0.87 to 1.02.
Homologues: Orthologues: chimpanzee CC2D1B (99% identical), macaque CC2D1B (96% identical), pig CC2D1B (87% identical), rabbit CC2D1B (86% identical), dog CC2D1B (86% identical), guinea pig CC2D1B (83% identical), rat Cc2d1b (81% identical), mouse Cc2d1b (81% identical), tropical clawed frog cc2d1b (55% identical), zebrafish cc2d1b (50% identical), Drosophila melanogaster l(2)gd1 (31% identical), Caenorhabditis elegans ccct-1 (27% identical). Paralogues in human: CC2D1A (45% identical).
Diseases named in the same sentence as CC2D1B in open-access papers:
CC2D1B is named in the same sentence as 11 diseases in open-access papers, as found by Europe PMC text mining. Sharing a sentence is not in itself a finding about the gene and the disease. The quoted sentences say what the papers report.
cognitive deficits (2 papers, 2018 to 2022). "When we tested the behavioral performance of 1b-KOs we found that Cc2d1b LOF caused only cognitive deficits, which are partially overlapping with those observed in Cc2d1a conditional LOF." (PMID 29552027, 2018). "In summary, loss of CC2D1B leads to cognitive deficits in both memory acquisition and retention." (PMID 29552027, 2018). "Because Cc2d1b KO mice present cognitive deficits, we sought to clarify the role of CC2D1B in oligodendrocytes during myelin formation." (PMID 35592111, 2022).
depression (2 papers, 2014 to 2022). "CC2D1B participate in a dual repressor element with Freud2, both molecules acting as strong repressors of the expression of serotonin 1A receptor, a key receptor involved in pathophysiology of depression and antidepressant drug response." (PMID 36386166, 2022). "We identify a set of conserved transcription factors including Deaf1, Freud-1/CC2D1A, Freud-2/CC2D1B and glucocorticoid receptors that may confer deleterious regional changes in 5-HT1A receptors in depression, and how future treatments could target these mechanisms." (PMID 24936175, 2014).
Anxiety (1 paper, 2018). Intense feelings of nervousness, tension, or panic often arise in response to interpersonal stresses. "Results from the 1a/1b-dHETs suggest that partial loss of Cc2d1a in combination with a half dosage of Cc2d1b is sufficient to generate hyperactivity and anxiety." (PMID 29552027, 2018). "We generated Cc2d1b knockout (KO), Cc2d1a/1b double heterozygous and double KO mice, then performed behavioral studies to analyze learning and memory, social interactions, anxiety, and hyperactivity." (PMID 29552027, 2018). "Both CC2D1A and CC2D1B are involved in learning and memory, while CC2D1A alone appears to contribute to anxiety and hyperactivity." (PMID 29552027, 2018). "Cc2d1b also differs from Cc2d1a, as it appears to have no role in social behavior, hyperactivity, and anxiety." (PMID 29552027, 2018).
autism spectrum disorder (1 paper, 2019). A spectrum of developmental disorders that includes autism, and Asperger syndrome. "Cc2d1a is highly expressed in neurons and has been implicated in intellectual disability and autism spectrum disorder, Cc2d1b is expressed in myelinating glial cells and peripheral nerves, which indicates that its role and function might not be fully redundant with Cc2d1a." (PMID 31379499, 2019).
demyelinating disease (1 paper, 2019). A broad group of disorders that affect the myelin sheaths that cover the neurons. "Elucidation of the upstream pathways and signals that induce CC2D1B and PURβ will be important both for understanding the molecular control of the myelination program, but also potentially for identifying strategies to promote remyelination in demyelinating disease." (PMID 31379499, 2019).
HIV-1 infection (1 paper, 2024). The type species of lentivirus and the etiologic agent of acquired immunodeficiency syndrome (AIDS). "To further examine the role of CC2D1B, we bypassed the early step of regular HIV-1 infection by utilizing env-defective single-round HIV-1 particles pseudo-typed with the VSV-G protein." (PMID 38714682, 2024).
melanoma (1 paper, 2013). A malignant, usually aggressive tumor composed of atypical, neoplastic melanocytes. "Specifically, FLRT2 was downregulated while MAD1L1, PHLDA2, PLAT, CC2D1B, CDKN2A and RUNX3 were upregulated in both melanoma and in Group 2 and Group 3 SFs." (PMID 23371019, 2013).
neurodevelopmental disorder (1 paper, 2018). A behavioral and cognitive disorder with onset during the developmental period that involves impaired or aberrant development of intellectual, motor, or social functions. "While this indicates that CC2D1B is not fully able to compensate in the brain leading to the human presentation, it is unclear whether CC2D1B itself could have a role in neurodevelopmental disorders." (PMID 29552027, 2018).
CC2D1B also shares sentences with these, for which no sentence is quoted: autism (1 paper); Intellectual disability (1); polyp (1).